RP1 (RP1 axonemal microtubule associated)
Diseases named in the same sentence as RP1 in open-access papers (continued):
Sharing a sentence is not in itself a finding about the gene and the disease.
colorectal cancer (3 papers, 2010 to 2022). A primary or metastatic malignant neoplasm that affects the colon or rectum. "It was also showed the knockout of lncRNA RP1-85f18.6, highly expressed in colorectal cancer, would promote pyroptosis." (PMID 35237509, 2022).
ovarian carcinoma (3 papers, 2015 to 2025). A malignant neoplasm originating from the surface ovarian epithelium. "Similarly, the BTB/POZ domain (Broad-Complex, Tramtrack and Bric-a-brac) contained within the region of the RP1-27O5.3 gene involved in the RP1-27O5.3–ZNF643 fusion has been previously implicated in ovarian cancer growth and recurrence." (PMID 26177635, 2015). "Previously, we have reported that Rp1 (5 μM) does not affect growth of drug-resistant ovarian cancer cells." (PMID 32151067, 2020).
COVID-19 (2 papers, 2023 to 2024). A disease caused by infection with severe acute respiratory syndrome coronavirus 2. "This analysis revealed multiple genomic loci associated with COVID-19 severity with or without asthma comorbidity, including DSP, HIP1 and RP1 genes." (PMID 38750426, 2024).
depression (2 papers, 2017 to 2024). "Multiple genes in these modules, including PTPRZ1 in adulthood and RP1-35C21.2 in childhood, are associated with susceptibility to schizophrenia and depression." (PMID 39472939, 2024).
malaria (2 papers, 2007 to 2016). Malaria is a serious and sometimes fatal disease caused by a parasite that commonly infects a certain type of mosquito which feeds on humans. "The gene shares 85% and 86% identity respectively with CYP6P4a (510 amino acids) and CYP6P4b (513 amino acids) from the other major malaria vector, An. funestus; the two duplicated P450s from rp1 QTL implicated in pyrethroid resistance." (PMID 26548743, 2016). "The rp1 QTL identified here represents a first step toward a fine mapping of genes involved in this resistance trait and by combining this approach with functional characterization of P450 genes on chromosome 2R we will elucidate the molecular basis of pyrethroid resistance in this malaria vector." (PMID 17261170, 2007).
night blindness (2 papers, 2006 to 2022). Inability to see clearly in dim light. "The majority of the patients who are heterozygous for the RP1 mutation show a type 2 autosomal dominant RP phenotype, with a relatively late onset of night blindness by the third or fourth decade of life." (PMID 16597330, 2006).
schizophrenia (2 papers, 2023 to 2024). A major psychotic disorder characterized by abnormalities in the perception or expression of reality. "As expected, the placental TWAS association with schizophrenia and IQ was discordant (r = −0.0929) and three genes (SNU13, WBP2NL, RP1-257I20.14) were significantly associated with schizophrenia and IQ with opposite sign." (PMID 37188697, 2023).
arterial hypertension (1 paper, 2022). "However, the RP1 protein is expressed in the kidneys, and it remains unclear why the mutation of this gene so far was only specifically related to retinal photoreceptor function and not to arterial hypertension and renal disease." (PMID 35886928, 2022).
astrocytoma (1 paper, 2019). "Though recurrent somatic mutations in IMSCTs were rare, we identified NF2 mutations in 15.7% of tumors (ependymoma, N = 7; astrocytoma, N = 1), RP1 mutations in 5.9% of tumors (ependymoma, N = 3), and ESX1 mutations in 5.9% of tumors (ependymoma, N = 3)." (PMID 31822682, 2019).
autosomal recessive rod-cone dystrophy (1 paper, 2015). "We report ophthalmic and genetic findings in families with autosomal recessive rod-cone dystrophy (arRCD) and RP1 mutations." (PMID 25692139, 2015).
blast (1 paper, 2015). "The maize rust resistance gene Rp1 and rice blast resistance gene Pi37 are orthologous and have high sequence similarity." (PMID 26424005, 2015).
Blindness (1 paper, 2006). Blindness is the condition of lacking visual perception defined as a profound reduction in visual perception. "Rp1-/- mice closely reflect very well the progressive blindness observed in human patients." (PMID 16869982, 2006).
ciliopathies (1 paper, 2014). "In agreement with the frequent involvement of both retinopathy and renal disease in ciliopathies, rs9362054 in RP1-90L14.1 was also significantly associated with DN." (PMID 25364816, 2014).
emphysema (1 paper, 2006). "The upregulation of the senescence-associated IGFBP-3 and -rP1 in emphysema suggests that inhibition of the action of insulin and insulin-like growth factors could be involved in the reduced in vitro-proliferation rate." (PMID 16504044, 2006). "The upregulation of IGFBP-3 and -rP1 can be taken as further evidence for a senescent phenotype in emphysema." (PMID 16504044, 2006).
ependymoma (1 paper, 2019). A WHO grade II, slow growing tumor of children and young adults, usually located intraventricularly. "With missense RP1 mutations observed in two classic ependymomas and one myxopapillary ependymoma and missense ESX1 mutations observed in one classic ependymoma, one myxopapillary ependymoma, and one subependymoma." (PMID 31822682, 2019). "The other two recurrently mutated genes in our IMSCT cohort, RP1 and ESX1, were observed in ependymomas as well." (PMID 31822682, 2019).
epilepsy (1 paper, 2006). A brain disorder characterized by episodes of abnormally increased neuronal discharge resulting in transient episodes of sensory or motor neurological dysfunction, or psychic dysfunction. "Mutations in the human DCX gene result in abnormal neuronal migration, epilepsy, and mental retardation; mutations in RP1 are associated with a form of inherited blindness, and DCDC2 has been associated with dyslectic reading disabilities." (PMID 16869982, 2006).
fish disease (1 paper, 2020). Diseases of freshwater, marine, hatchery or aquarium fish. "It is noteworthy that the Fc-RP1 peptide synthesized here is a prototype of a bioconjugation strategy, but it still is a compound with great biological activity against neglected and fish diseases." (PMID 32214347, 2020). "It is noteworthy that even with the Fc-RP1 peptide being a prototype of a bioconjugation strategy; it still is a compound with great biological activity against neglected tropical diseases and fish diseases." (PMID 32214347, 2020).
gallstones (1 paper, 2024). Solid crystalline precipitates in the biliary tract, usually formed in the gallbladder, resulting in the condition of cholelithiasis. "The results indicated that AC004692.4, HECW1-IT1, SFRP4, and COMP were significantly higher expressed in gallstone samples, whereas LINC01564, SLC26A3, RP1-27K12.2, and GSTA2 were markedly lower expressed in gallstone samples compared to control samples." (PMID 38808330, 2024). "Furthermore, using RT-qPCR, we observed significant upregulation of AC004692.4, HECW1-IT1, SFRP4, and COMP, while LINC01564, SLC26A3, RP1-27K12.2, and GSTA2 exhibited marked downregulation in gallstone samples." (PMID 38808330, 2024).
glomerulosclerosis (1 paper, 2019). A hardening of the kidney glomerulus caused by scarring of the blood vessels. "Histopathological assessment of glomerulosclerosis showed that the number of sclerotic glomeruli was significantly greater in Rp18.0 when compared with Rp1.0 and SHR." (PMID 30792992, 2019).
leiomyoma (1 paper, 2022). A well-circumscribed benign smooth muscle neoplasm characterized by the presence of spindle cells with cigar-shaped nuclei, interlacing fascicles, and a whorled pattern. "Our data indicated increased expression of RP1-170O19.14 and its proximal gene HOXA11 in leiomyomas." (PMID 35641855, 2022).
mesothelioma (1 paper, 2016). A usually malignant and aggressive neoplasm of the mesothelium which is often associated with exposure to asbestos. "It remains, however, to determine whether regulatory Rp-1+ PMN-MDSC infiltrate mesotheliomas in long-term studies with CNT-treated rats as proposed in other models." (PMID 27549627, 2016).
Nystagmus (1 paper, 2021). Rhythmic, involuntary oscillations of one or both eyes related to abnormality in fixation, conjugate gaze, or vestibular mechanisms. "We found that the RP1-Alu variant along with other frameshift mutations can cause childhood-onset retinal dystrophy with nystagmus, mimicking LCA or Stargardt disease." (PMID 34183725, 2021).
osteoporosis (1 paper, 2025). A condition of reduced bone mass, with decreased cortical thickness and a decrease in the number and size of the trabeculae of cancellous bone (but normal chemical composition), resulting in increased fracture incidence. "The results of the analysis on BMD and osteoporosis were subsequently structured, uncovering four shared genes in IBD: ZBTB40, RP1-135L22.1, RSPO3, and RP11-103J8.1." (PMID 41264632, 2025).
pancreatic cancer (1 paper, 2013). "Recent findings have indicated an involvement of RP1 in highly nerve invasive pancreatic cancer cells." (PMID 23844040, 2013). "Pancreatic cancer cells examined by immunofluorescence have a specific cellular pattern for RP1 and actin." (PMID 23844040, 2013).
preeclampsia (1 paper, 2014). Preeclampsia is a hypertensive disorder of pregnancy that is characterized by new-onset hypertension with proteinuria presenting after 20 weeks of gestation, and depending on mild or severe forms may initially present with severe headache, visual disturbances, and hyperreflexia. "In the present study we found that RP1/RP2 and RP2/RP2 genotypes and RP2 allele could be risk factors in predisposing to preeclampsia in our population." (PMID 24877103, 2014).
type 2 diabetes (1 paper, 2022). "Two loci, EHMT2 (lead SNP rs1265945) and lincRNA RP1-230L10.1 (lead SNP rs66930764), shared by type 2 diabetes and chronotype, were duplicated in FI." (PMID 35203577, 2022).
viral infections (1 paper, 2024). "A recent study highlighted the significance of RP1 in association with SARS-CoV-2 and Middle East respiratory syndrome (MERS) viruses, indicating its role in facilitating viral infections and severe disease complications." (PMID 38750426, 2024).
cancer (16 papers, 2006 to 2025). A tumor composed of atypical neoplastic, often pleomorphic cells that invade other tissues. "Only the three remaining genes, KCNQ3, LRRC38 and RP1, were rarely reported in any cancer research, and thus show potential value for research in LUSC." (PMID 35962453, 2022). "We also found that only RP1-261G23.7 was involved in the Wnt signal pathway, which is in a variety of biological processes, including cell cycle regulation and cancer." (PMID 31850493, 2020). "The largest FMGS identified in all these cancer stages contained 8 genes (k = 8; RP1, PCDHAC2, TENM3, SPHKAP, ODZ3, ADAMTS18, SCN5A, PKHD1L1) found in SKCM-stage IV." (PMID 27556693, 2016). "Regulatory neutrophilic MDSC (PMN-MDSC) that highly express Rp-1, a marker of undifferentiated neutrophils, have been detected in rat bearing carcinoma." (PMID 27549627, 2016). "Taken together, our results suggest that ActD in combination with Rp1 may be an effective chemotherapeutic strategy for overcoming drug resistance of cancer cells." (PMID 32151067, 2020). "In current study we found that RP-1, a specific peptide binding to CD44 protein, exhibited the potentials of specific binding to CD44 high-expressing cancer cells both in vitro and in vivo, and the capacity of predicting prognosis of human GC in a microarray assay." (PMID 28415792, 2017).
tumor (12 papers, 2010 to 2025). "Of the 10 pivotal ceRNAs, CTB-63M22.1, and RP1-241P17.4 were associated with tumor prognosis." (PMID 31156552, 2019). "Among the downregulated DEGs, four genes (LAMA1, ASPRV1, IL1B, PRR4) displayed reduced expression, while two genes (CCDC157, RP1) showcased elevated expression in tumor compared to normal tissue, respectively." (PMID 39062832, 2024). "More, tumor growth was significantly inhibited when ActD combined with Rp1 in nude mice implanted with LS513 cells as well." (PMID 34975466, 2021). "While ActD and Rp1 had a limited effect on their own, they effectively hindered tumor growth when used in combination." (PMID 32151067, 2020). "RP1 has likewise been shown to modulate cholesterol levels and disrupt lipid raft organization, leading to downregulation of P-gp expression and inhibition of Src phosphorylation, thereby reversing the resistance of tumor cells to actinomycin D." (PMID 41304944, 2025). "After colon cancer cells were exposed to conditioned medium from radiation-potentiated macrophages, it was found that culture supernatant of Rp1-treated macrophages inhibited growth and metastasis of tumor cells and prolonged survival of tumor-bearing mice in vivo." (PMID 35002732, 2021). "Taken together, these results suggest that SIRT1 overexpression is associated with ActD resistance, and that inhibiting SIRT1 with Rp1 could be of therapeutic benefit to overcome drug resistance in tumor cells." (PMID 32151067, 2020). "Furthermore, these two cases shared a common five-member mutant cell surface receptor signature as well (DSCAM, IGSF21, GHR, GRINA2 and RP1), suggesting that they may also have been involved in the massive antitumoral response to the primary tumor." (PMID 36980598, 2023). "Meanwhile, co-treatment of Rp1 and ActD also decreased AKT activation to downregulate the expression of SIRT1, and ultimately activated cells apoptosis as well as reversed chemoresistance in tumor cells." (PMID 34975466, 2021).
infection (6 papers, 2011 to 2023). The state of being infected such as from the introduction of a foreign agent such as serum, vaccine, antigenic substance or organism. "Whereas the BALF was nearly devoid of neutrophils at baseline, infection led to a significant increase in the number of RP1-positive cells." (PMID 37366533, 2023). "In contrast to many classical antimicrobial peptides, RP-1 has striking antimicrobial efficacy when administered intravenously in rigorous models of infection in vivo." (PMID 22073187, 2011). "Neutrophil infiltrates (CD45+ CD11b+ RP1+) were significantly increased in the CSF of animals implanted with S. epidermidis-infected versus sterile catheters (P = 0.001), consistent with human shunt infection." (PMID 31262978, 2019). "By comparing virus-infected samples to healthy samples, we identified 160 and 22 DEGs in response to infection with BBWV2-PAP1 and RP1, respectively." (PMID 34721473, 2021). "The leaves infected with BBWV2-PAP1 showed more intense staining than BBWV2-RP1-infected leaves, indicating that ROS accumulation was specifically elevated by infection with BBWV2-PAP1 but not RP1." (PMID 34721473, 2021). "An intragenic recombination between paralogs Rp1-D and Rp1-dp2 produced the chimeric gene Rp1-D21, which was identified on the basis of its ‘lesion mimic’ phenotype in the absence of pathogen infection." (PMID 25719542, 2015).
retinal disorder (5 papers, 2014 to 2025). Any disease or disorder of the retina. "Several candidate genes associated with CQ/HCQ retinopathy were found with exome sequencing, including RP1L1, RPGR, RPE65, CACNA2D4, EYS, RP1, IMPG1 and ABCA4." (PMID 38548946, 2024). "Interestingly, other cases of concurrent retinal disorders have been explained by the presence of p.M390R and mutations in the arRP-associated genes C2ORF71 and RP1." (PMID 25494902, 2014).
degenerative diseases (2 papers, 2006 to 2014). "Recently, RP1 has also been shown to be a microtubule-associated protein forming part of the larger class of MAP proteins, whose dysfunction is associated with degenerative diseases." (PMID 16597330, 2006).
autosomal dominant disease (1 paper, 2021). Autosomal dominant form of disease. "Variants in RP1 were the most common cause of autosomal dominant disease (n = 19, 31.7%)." (PMID 33749171, 2021).
RP1 also shares sentences with these, for which no sentence is quoted: retinitis pigmentosa 1 (4 papers); lung carcinoma (3); Crohn disease (2); glaucoma (2); Leber congenital amaurosis (2); renal disease (2); thyroid cancer (2); Usher syndrome (2); achromatopsia (1); asthma (1); autism (1); autoimmune disease (1); Autoimmunity (1); Bardet-Biedl syndrome (1); campomelic dysplasia (1); choroideremia (1); colorectal adenocarcinoma (1); cone dystrophy (1); congenital disorder of glycosylation (1); deafness (1); dysplasia (1); Fanconi anemia (1); gastric cancer (1); hepatocellular carcinoma (1); Insulin resistance (1); keratoconus (1); lymph-node metastasis (1); meningioma (1); metabolic syndrome (1); myopia (1).
A further 4 diseases each share a sentence with RP1 in 1 paper.